METTL14 (methyltransferase 14, N6-adenosine-methyltransferase non-catalytic subunit)
Diseases named in the same sentence as METTL14 in open-access papers (continued):
Sharing a sentence is not in itself a finding about the gene and the disease.
colorectal cancer (continued). "In colorectal cancer, the lack of METTL3 or METTL14 increases cytotoxic tumor-infiltrating CD8+ T cells; enhances the production of interferon- (IFN-) γ, CXCL9, and CXCL10; and promotes the recruitment of CD8+ and CD4+ effector T cells that inhibit tumor growth." (PMID 34858499, 2021).
acute myeloid leukemia (72 papers, 2018 to 2026). Acute myeloid leukemia (AML) is a group of neoplasms arising from precursor cells committed to the myeloid cell-line differentiation. "METTL3 and METTL14, key components of the m6A writer complex, are frequently overexpressed in various malignancies, including acute myeloid leukemia (AML), where aberrant methylation has been linked to the upregulation of oncogenic transcription." (PMID 41245600, 2025). "Research has found that STM2457 can inhibit the catalytic activity of METTL3/METTL14, targeting populations of acute myeloid leukaemia (AML) key stem cells with an IC50 = 16.9 nM and it is identified as a specific METTL3 inhibitor." (PMID 39779466, 2025). "For example, METTL3 and METTL14 exhibited an oncogenic role in acute myeloid leukemia (AML), in which they were highly expressed and correlated with shorter survival." (PMID 38503745, 2024). "METTL14 shows high expression levels in normal hematopoietic stem/progenitor cells (HSPCs) and acute myeloid leukemia (AML) cells carrying t (11q23), t, or t translocations." (PMID 39473440, 2024). "Downregulation of METTL14 was also reported in glioma, whereas high expression levels in acute myeloid leukemia cells enhanced leukemogenesis." (PMID 35474700, 2021). "For instance, METTL14 can function as an oncogene in acute myeloid leukemia 28 and simultaneously suppress the metastatic potential of HCC by modulating m6A dependent primary microRNA processing." (PMID 34659574, 2021). "Recent studies demonstrated that loss of METTL3, METTL14, or FTO weakens acute myeloid leukemia (AML) propagation, whereas inactivation of METTL3 and METTL14 has deleterious consequences for normal HSC maintenance." (PMID 33156926, 2021). "The mutations of m6A regulatory genes, METTL3, METTL14, YTHDF1, YTHDF2, FTO, and ALKBH5, have been identified in acute lymphoblastic leukemia, multiple myeloma, and acute myeloid leukemia (AML)." (PMID 33898522, 2021). "Like the dual role of METTL3, it was also reported that METTL14 acts as an oncogene in acute myeloid leukemia (AML) and breast cancer 49,50." (PMID 33456561, 2021). "Similar to METTL3, METTL14 was also proved to accelerate the progression of acute myeloid leukemia (AML)." (PMID 34211849, 2021). "In contrast, METTL14 is highly expressed in acute myeloid leukemia cells and promotes leukemogenesis via m6A modification." (PMID 33134390, 2020). "Highly expressed in normal hematopoietic stem cells, METTL14 impeded myeloid differentiation and showed oncogenic function via m6A modification of its target mRNA in acute myeloid leukemia." (PMID 32710725, 2020). "It has been reported that the expression of Mettl14 is negatively regulated by SPI1 in acute myeloid leukemia (AML) cells." (PMID 32444598, 2020). "METTL14 is highly expressed in normal hematopoietic stem/progenitor cells and acute myeloid leukemia cells." (PMID 31226160, 2019). "For the first time, Weng and coworkers described the signaling axis SPI1-METTL14-MYB/MYC in normal myelopoiesis and leukemogenesis and proposed that METTL14 could be a new therapeutic target to treat acute myeloid leukemia (AML)." (PMID 40940799, 2025). "Despite numerous studies suggesting that RNA m6A transferase core complex including METTL3 and METTL14 play essential roles in both the initiation and maintenance of acute myeloid leukemia (AML), effective pharmacological targeting of these two proteins remains elusive." (PMID 40453361, 2024). "METTL14 is highly expressed in acute myeloid leukemia cells and exerts its oncogenic role." (PMID 33816306, 2021). "METTL14 exerted an oncogenic role in acute myeloid leukemia via mRNA m6A modification." (PMID 34863142, 2021). "Some reports show that METTL14 is supposed to be an oncogene in acute myeloid leukemia." (PMID 32903675, 2020). "Core components of the m6A machinery, including METTL3, METTL14, FTO, and ALKBH5, have been implicated in acute myeloid leukemia (AML) pathogenesis." (PMID 40973767, 2025).
acute myeloid leukemia (continued). "In acute myeloid leukemia (AML), AML-derived mesenchymal stem cells (AML-MSCs) deliver METTL14 to leukemia cells via exosomes, where it stabilizes ROCK1 expression through the m6A-IGF2BP3 axis, thereby mediating radioresistance." (PMID 40823093, 2025). "LncRNA UCA1 promotes acute myeloid leukemia (AML) progression by affecting the stability of METTL14 and upregulating the expression of CXCR4 and cytochrome P450 family 1 subfamily B member 1 (CYP1B1)." (PMID 38351139, 2024). "The expression of METTL14 was decreased in acute myeloid leukemia (AML), which affects m6A modification and thus promotes AML development, proving that METTL14 is a prognostic biomarker for AML." (PMID 39289775, 2024). "METTL14 was highly expressed in normal hematopoietic stem/progenitor cells (HSPCs) and acute myeloid leukemia (AML) cells and was downregulated during myeloid differentiation." (PMID 36835633, 2023). "It was found that METTL3 and METTL14 (writers) served an oncogenic role in acute myeloid leukemia (AML) in an m6A manner by promoting the translation of MYC, MYB, BCL2, SP1, and PTEN." (PMID 36281789, 2022). "METTL3 and METTL14 are upregulated in acute myeloid leukemia (AML) where they have an established oncogenic function and play a relevant role in AML survival." (PMID 34561421, 2021). "The downregulation of METTL3 and METTL14 can induce the apoptosis and differentiation of acute myeloid leukemia (AML) cells." (PMID 33952721, 2021). "In acute myeloid leukemia (AML), METTL14 is also found to be highly expressed, silencing of which led to inhibition of cellular proliferation and reduced survival of AML cells." (PMID 32194861, 2020). "For instance, the METTL3 and METTL14, highly expressed in acute myeloid leukemia (AML), play a critical role in leukemia progression through promoting translation of target mRNAs, including MYB, MYC, BCL2, and PTEN." (PMID 33292652, 2020). "Additionally, METTL14 is required for the development and sustenance of acute myeloid leukemia (AML) and leukemic stem/initiating cells (LSCs/LICs)." (PMID 40819104, 2026). "METTL14 was found to be negatively regulated by the SPI1 transcription factor both in normal and pathological conditions such as acute myeloid leukemia." (PMID 40940799, 2025). "In contrast, METTL14 is highly expressed in acute myeloid leukemia (AML) cells, where silencing it induces terminal myeloid differentiation in both AML and normal hematopoietic stem and progenitor cells (HSPCs), thereby preventing AML cell survival and proliferation." (PMID 40271153, 2025). "Several studies have indicated that METTL3, METTL14, and WTAP are highly expressed in patients with acute myeloid leukemia (AML) and function as oncogenes." (PMID 40171845, 2025). "For example, methyltransferases METTL3 and METTL14 enhance translation efficiency by adding m6A marks to MYC, a process that supports rapid proliferation in acute myeloid leukemia (AML)." (PMID 41446042, 2025). "In acute myeloid leukemia, the overexpression of METTL3/METTL14 enhances the stability and translation efficiency of c-myc via m6A modifications, thereby accelerating cancer progression." (PMID 38965238, 2024). "In acute myeloid leukemia, METTL3 and METTL14 exhibit binding to transcription start sites, but the binding sites of METTL3 and METTL14 are almost entirely distinct." (PMID 38965238, 2024). "METTL14 promotes tumorigenesis by upregulating expression of MYC and MYB in acute myelocytic leukaemia (AML) but acts as a tumor suppressor by inactivating AKT in endometrial cancer." (PMID 35047058, 2022). "In acute myeloid leukemia (AML), METTL14 regulates MYB and MYC via M6A modification, and plays a carcinogenic role in regulating cell self-renewal and inhibiting bone marrow differentiation." (PMID 35552266, 2022).
acute myeloid leukemia (continued). "In this study, we investigated the expression of methyltransferase-like 3 (METTL3) and 14 (METTL14), components of the RNA m6A methyltransferase complex, in samples from 89 patients with acute myeloid leukemia (AML), and followed the survival of 75 of these patients." (PMID 35154467, 2022). "METTL14, an essential element of the m6A writer complex, has been found to be highly expressed in both normal hematopoietic stem cells (HSCs) and acute myeloid leukemia (AML) cells; however, its expression decreases when these cells begin to differentiate." (PMID 34586737, 2021). "In acute myeloid leukemia (AML), abnormal expression of m6A regulatory factors, including METL3, METTL14, FTO, ALKBH5, and IGF2BP1/2/3, can regulate the expression of MYC." (PMID 33926508, 2021). "In acute myeloid leukemia (AML), both METTL3 and METTL14 can directly target MYC to enhance its translation efficacy and inhibit differentiation and increase proliferation." (PMID 34315512, 2021). "In acute myeloid leukemia (AML), the m6A writer METTL14 was found upregulated." (PMID 32194861, 2020). "Furthermore, in acute myeloid leukemia (AML), METTL3, operating independently of METTL14, is recruited to chromatin by the CAATT-box binding protein CEBPZ and localizes to the transcription start site to regulate the translation of target genes." (PMID 38444581, 2024). "They found that in acute myeloid leukemia (AML), METTL3 could be localized to the transcription initiation site of target genes in chromatin independently of METTL14 which was essential for m6A modification." (PMID 36830614, 2023). "In particular, acute myeloid leukemia (AML), one of the most common types of leukemia with diverse genetic and molecular abnormalities in adults, expresses higher levels of METTL3 and METTL14 compared with other cancer types in the analysis of The Cancer Genome Atlas (TCGA) dataset." (PMID 35455436, 2022). "UCA1 stabilizes METTL14 allowing the writer to deposit m6A marks on target mRNAs, such as CYP1B1 and CXCR4, leading to acute myeloid leukemia (AML) development." (PMID 39280246, 2024). "In acute myeloid leukemia (AML), METTL3 and METTL14 have been already described as regulators of mRNA translation." (PMID 34561421, 2021). "It was reported that METTL14 overexpression in acute myeloid leukemia is negatively regulated by SPI1 and mediates downstream targets, MYB and MYC, to accelerate acute myeloid leukemia (AML) oncogenesis." (PMID 34904301, 2022). "METTL14 regulates mRNA stability and the translation of MYB and MYC genes, players in the self-renewal and differentiation of normal HSCs and acute myeloid leukemia (AML) cells." (PMID 32916783, 2020). "In addition, METTL3 depletion in HSCs did not affect apoptosis, whereas knocking down of METTL14 induced acute myeloid leukemia (AML) cell apoptosis and promoted myeloid differentiation of normal HSCs via the SPI1–METTL14–MYB/MYC signaling axis." (PMID 35935968, 2022).
pancreatic cancer (56 papers, 2019 to 2026). "METTL14 has been identified as an oncogene in pancreatic cancer, as its depletion increases susceptibility to cisplatin-induced apoptosis in PANC-1 and CFPAC-1 cells." (PMID 38665783, 2024). "This phosphorylation event subsequently inhibits exon 10 skipping in METTL14, resulting in an up‐regulation of the METTL14‐Lexon10+ variant and a down‐regulation of the METTL14‐Lexon10− variant in pancreatic cancer." (PMID 37850412, 2023). "The increase in the m6A methylation levels in pancreatic cancer is caused by an imbalance in the level of the m6A regulatory factor METTL14." (PMID 34246319, 2021). "Loss of METTL14 increased apoptosis induced by cisplatin in pancreatic cancer cells, and autophagy was enhanced through an mTOR signaling-dependent pathway." (PMID 34239358, 2021). "Another study showed that high METTL14 expression in pancreatic cancer tissues is associated with clinicopathological variables." (PMID 34239358, 2021). "Overall, our results indicated that METTL14 was up-regulated in gemcitabine resistant pancreatic cancer cell lines, and its expression was functionally linked to gemcitabine resistance." (PMID 34458141, 2021). "In summary, our study revealed elevated levels of m6A methylation in pancreatic cancer caused by the dysregulation of METTL14, an m6A modulator." (PMID 32843065, 2020). "Conversely, METTL14 is overexpressed in gemcitabine-resistant pancreatic cancer cells and mediates the up-regulation of cytidine deaminase, promoting gemcitabine resistance in pancreatic cancer." (PMID 40483535, 2025). "METTL14 expression is significant in pancreatic cancer and collaborates with METTL3 to enhance Inhibitingthe inhibition of DNA binding 2 mRNA stability through m6A modification." (PMID 39791162, 2025). "For instance, in pancreatic cancer, METTL14 is upregulated, leading to decreased PERP levels through the m6A‐YTHDF2 axis, thereby promoting cancer growth and metastasis." (PMID 39021049, 2024). "For example, METTL14 is highly expressed in pancreatic cancer tissues, and the upregulation of METTL14 decreases PERP levels via m6A modification, promoting the growth and metastasis of pancreatic cancer." (PMID 38725005, 2024). "METTL14 is up-regulated in pancreatic cancer and down-regulation of METTL14 improves autophagy through mTOR signaling-dependent pathways." (PMID 39289775, 2024). "For instance, METTL14 inhibits autophagy in testicular tissues and pancreatic cancer, whereas METTL3 promotes autophagy in the heart, liver, and endothelial cells." (PMID 36632456, 2023). "To explore the potential mechanisms of METTL14, we performed RNA-seq in sh-NC and sh-METTL14 pancreatic cancer cells (PANC-1)." (PMID 37215454, 2023). "They reported that METTL14 was overexpressed in gemcitabine-resistant pancreatic cancer cells and p65 (a transcription factor) promoted the expression of METTL14 and subsequently upregulated cytidine deaminase (CDA), a gemcitabine inhibitor." (PMID 37264402, 2023). "To investigate the clinicopathological features of METTL14 in pancreatic cancer, we scored the staining in the TMA." (PMID 37215454, 2023). "For example, m6A methylation levels are significantly higher in approximately 70% of pancreatic cancer samples, and dysregulation of METTL14 can affect m6A levels in pancreatic cancer cells." (PMID 37805597, 2023). "In pancreatic cancer, transcription factor P65 positively regulates METTL14 expression by interconnecting with the promoter region of METTL14." (PMID 34904301, 2022). "In pancreatic cancer, METTL14 promotes cell proliferation and migration via directly targeting PERP in an m6A-dependent manner." (PMID 36288387, 2022). "The upregulation of METTL14 has been demonstrated to lead to the decrease of PERP level through m6A modification which promotes the metastasis and growth of pancreatic cancer; thus, METTL14 can be a potential therapeutic target for pancreatic cancer." (PMID 35487915, 2022).
pancreatic cancer (continued). "For instance, METTL14 promotes pancreatic cancer cell proliferation and migration, which relies on its methyltransferase activity." (PMID 36291811, 2022). "We found that gemcitabine treatment significantly increased the expression of m6A methyltransferase METTL14, and METTL14 was up-regulated in gemcitabine-resistance human pancreatic cancer cells." (PMID 34458141, 2021). "In pancreatic cancer, upregulation of METTL14 expression was reported to lead the reduction of PERP levels via m6A modification, thus promoting the metastasis of PC." (PMID 33849617, 2021). "Our study suggested that METTL14 is a potential target for chemotherapy resistance in pancreatic cancer." (PMID 34458141, 2021). "The promotion function by METTL14 in pancreatic cancer was uncovered and IGF2BP3 was found to be a potential prognosis marker and therapeutic target of colon cancer." (PMID 33718187, 2021). "We have determined the role of METTL14 in promoting the resistance of gemcitabine in pancreatic cancer cells." (PMID 34458141, 2021). "Next, we examined the role of METTL14 in invasion and metastasis in the context of pancreatic cancer." (PMID 32843065, 2020). "To further examine the association between PERP and METTL14 expression, we performed immunofluorescence assays in pancreatic cancer tissues, and observed that tumor cells with high METTL14 expression showed low PERP expression, and vice versa." (PMID 32843065, 2020). "In this study, we further highlight the importance of abnormal mRNA methylation-related gene expression (and the consequent biological functions), particularly in the context of METTL14 knockdown in human pancreatic cancer cells." (PMID 32843065, 2020). "Together, these data indicate that METTL14 plays an important role as a promotor of pancreatic cancer growth and metastasis." (PMID 32843065, 2020). "Here, we present the first study on the expression of METTL14, one of the main m6A regulators, in pancreatic cancer." (PMID 32843065, 2020). "To assess the biological role of METTL14 in pancreatic cancer, we overexpressed or knocked down METTL14 in human pancreatic cancer cell lines." (PMID 32843065, 2020). "Together, these data suggest that METTL14 is a major m6A regulating factor, involved in the clinicopathology of pancreatic cancer." (PMID 32843065, 2020). "We identified METTL14 as the primary regulator of m6A, which suggests a new focus for targeted pancreatic cancer treatment development." (PMID 32843065, 2020). "In this study, we further found that PERP is an essential METTL14 target gene in pancreatic cancer, obviously in an m6A-dependent manner." (PMID 32843065, 2020). "To investigate the regulatory role of METTL14 in pancreatic cancers, we performed RNA-Seq to analyze the gene expression profiles of PANC-1 cells, control or METTL14 deficient." (PMID 32843065, 2020). "We show for the first time that METTL14 functions as an oncogene, promoting the growth and metastasis of pancreatic cancer." (PMID 32843065, 2020). "We also demonstrated the critical role of METTL14 in the growth and metastasis of pancreatic cancer via targeting of PERP mRNA." (PMID 32843065, 2020). "Mechanistically, m6A imbalance promotes oncogenesis by altering tumorsuppressor and oncogene signaling—exemplified by METTL14-driven m6Amodifications accelerating pancreatic cancer metastasis, and viral-induced METTL3overexpression exacerbating esophageal carcinoma progression." (PMID 40521894, 2025).